CLPSL2 (colipase like 2)
Synonyms: C6orf126; dJ510O8.5; UNQ3045; AAAL3045
Tractability: Antibody: UniProt places it where antibodies can reach, with high confidence; UniProt predicts a signal peptide or a membrane-spanning region; its Gene Ontology location is reachable by antibodies, with medium confidence.
Gene: Protein-coding gene on chromosome 6 (35,776,535 to 35,779,557, forward strand). Ensembl gene ENSG00000196748.
Subcellular location: Secreted
Subcellular location (Human Protein Atlas): Vesicles; Predicted to be secreted
Gene Ontology:
Molecular function: protein binding; enzyme activator activity
Biological process: digestion; lipid catabolic process
Cellular component: acrosomal vesicle; extracellular region; sperm flagellum
Genetic constraint (gnomAD): Loss-of-function variants: 4 observed, 6.68 expected, observed/expected ratio (o/e) 0.6, 90% interval 0.29 to 1.36. That is too few expected variants to judge how well the gene tolerates losing a copy. Missense variants: 132 observed, 114.86 expected, observed/expected ratio (o/e) 1.15, 90% interval 1 to 1.33. Synonymous variants: 67 observed, 42.76 expected, observed/expected ratio (o/e) 1.57, 90% interval 1.28 to 1.88.
Homologues: Orthologues: chimpanzee CLPSL2 (75% identical), pig CLPSL2 (65% identical), dog CLPSL2 (63% identical), mouse Clpsl2 (53% identical), rat Clpsl2 (47% identical). Paralogues in human: CLPS (25% identical), LRCOL1 (23% identical), CLPSL1 (20% identical).
Diseases named in the same sentence as CLPSL2 in open-access papers:
CLPSL2 is named in the same sentence as 1 disease in open-access papers, as found by Europe PMC text mining. Sharing a sentence is not in itself a finding about the gene and the disease. The quoted sentences say what the papers report.
cancer (2 papers, 2020). A tumor composed of atypical neoplastic, often pleomorphic cells that invade other tissues. "Best predicted cancer immunotherapy proteins with BC were RPS27, SUPT4H1, CLPSL2, POLR2K and RPL38, and the most altered ones were POLR2K, ASH2L, MED30, NSL1 and RPRD2." (PMID 32444848, 2020). "The best ranked cancer immunotherapy proteins related to BC were RPS27, SUPT4H1, and CLPSL2." (PMID 33537063, 2020).